NRG1 (neuregulin 1)
Diseases named in the same sentence as NRG1 in open-access papers (continued):
Sharing a sentence is not in itself a finding about the gene and the disease.
thyroid cancer (8 papers, 2014 to 2023). "This was confirmed in Koreans, where the risk alleles were also found to be associated with higher expression of NRG1 in normal thyroid and thyroid cancer tissues." (PMID 36476495, 2022). "Genome-wide association studies identified a SNP within intron 1 of the NRG1 gene to be strongly associated with thyroid cancer (p < 10− 9) in European populations." (PMID 36476495, 2022). "Whole-genome sequence analysis has revealed the association between NRG1 and free thyroxine, while it has also been found to influence the predisposition to thyroid carcinoma." (PMID 34568330, 2021). "Our clinical results also showed that the variants of NRG1 are associated with lymph node metastasis in thyroid cancer, especially in BRAFV600E-mutated PTC." (PMID 28703219, 2017). "NRG1 encodes neuregulin, a signaling protein recently identified in a study to be associated with thyroid cancer, potentially mediated by regulation of TSH levels." (PMID 25436638, 2014). "The NRG1 pathway has been implicated in thyroid cancer pathogenesis at many levels." (PMID 36476495, 2022). "Therefore, we conducted both GWAS and eQTL studies to identify potential susceptibility loci for thyroid cancer in Koreans and identified a strong association of the NRG1 gene and a modest association of six new genes in this population." (PMID 28703219, 2017). "That is, the NRG1 region could be an important risk gene for the susceptibility or prognosis of thyroid cancer." (PMID 28703219, 2017). "However, the effect of FOXE1 variants on thyroid cancer risk seemed to be less significant than that of NRG1 in this Asian population." (PMID 28703219, 2017). "Thus, the upregulated NRG1 expression could be associated with thyroid cancer development, especially in BRAFV600E mutation positive PTC." (PMID 28703219, 2017). "SNP rs2439302 was within the first intron of NRG1 on 8p12, which was first described to be significantly correlated with thyroid cancer." (PMID 37484916, 2023). "The NRG1 pathway was the top IPA gene expression signature induced by Yap in BrafV600E-driven thyroid cancers in vivo." (PMID 36476495, 2022). "Intriguingly, vemurafenib treatment of BRAF-mutant thyroid cancer cell lines induced translocation of Yap to the nucleus and activation of its transcriptional output, which included key effectors in the NRG1 signaling pathway." (PMID 36476495, 2022). "Several studies have reported that NRG1 is a predisposition to papillary thyroid cancer, but no genetic variant of NRG1 has been reported about the association with the thyroid cancer risk." (PMID 33805984, 2021). "In conclusion, BRAF-mutant thyroid cancer cells with constitutive activation of YAP transcriptional activity have intrinsic resistance to RAF kinase inhibitors, driven in part by increased expression of the upstream components of the NRG1 signaling pathway." (PMID 36476495, 2022).
cannabis dependence (7 papers, 2013 to 2023). Physical and psychological dependence on the drug cannabis. "The association of NRG1 variants with cannabis dependence in humans and independent preclinical evidence for a role of Nrg1 in initial response to cannabinoids is striking." (PMID 34367237, 2021). "A recent study demonstrated that NRG1 increased the risk of cannabis dependence in African-Americans." (PMID 23447498, 2013). "A genome-wide linkage scan, and follow-up association analysis, for cannabis dependence in African-American and European-American families, revealed that NRG1 variation was associated with increased risk for cannabis dependence in African-Americans, and this effect was pronounced in females." (PMID 27725886, 2016). "It has been outlined that there might be genetic subgroups in the population that are more vulnerable to particular environmental risk factors (e.g., cannabis abuse, developmental trauma) and NRG1 might be such a genetic candidate." (PMID 23966917, 2013). "The clinical relevance of this research has recently been highlighted by a genetic study in African Americans, which discovered NRG1 as a major candidate for the development of cannabis dependence." (PMID 23966917, 2013).
Hyperglycemia (7 papers, 2013 to 2025). An increased concentration of glucose in the blood. "Deletions in RBPJ-binding sites causes hyperglycemia-controlled Nrg1 levels to be downregulated, resulting in decreased tumor growth in vitro and in vivo." (PMID 36707514, 2023). "However, molecular mechanisms underlying hyperglycemia-induced Nrg1 overexpression remain poorly understood." (PMID 36707514, 2023). "These three species might therefore have contributed to JMT induced improvements in DPN phenotypes and symptoms of hyperglycemia and weight loss associated with increased serum NRG1 level." (PMID 32920546, 2020). "Based on this, we used a DNA pull-down assay to analyze the specific transcriptional (co)factors that bind to the Nrg1 active enhancer in response to hyperglycemia." (PMID 36707514, 2023). "Collectively, these results strongly indicate that Notch activation, which recruits Rbpj to the Nrg1 enhancer, is required for hyperglycemia-induced Nrg1 overexpression." (PMID 36707514, 2023). "Here, the induction of Gfra1 and Nrg1 may reflect adaptive metabolic or growth-factor signaling in response to hyperglycemia, whereas decreased expression of Aspdh and Mtch2 suggests compromised mitochondrial function and heightened oxidative challenges." (PMID 40920692, 2025). "Furthermore, a recent study demonstrated hyperglycemia leads to epigenetic up-regulation of the NRG1 gene (HER3 ligand)." (PMID 25400118, 2014). "NRG1 protein levels were also consistently lower in ΔE-250 and ΔE-Rbpj cells treated with HG compared with wild-type cells, indicating that the Nrg1 enhancer plays a crucial role in hyperglycemia-induced Nrg1 expression and functions at least in part through Rbpj." (PMID 36707514, 2023).
injury (7 papers, 2011 to 2025). Damage inflicted on the body as the direct or indirect result of an external force, with or without disruption of structural continuity. "NRG1 signalling imbalances can cause nerve injury and worsen pain." (PMID 41440136, 2025). "Several studies have shown that the overexpression of Nrg1 not only promotes cardiomyocyte proliferation in mice but also improves cardiac function after heart injury." (PMID 33928078, 2021). "We have recently shown that neuregulin-1, a growth factor released following nerve injury, activates erbB 2, 3, and 4 receptors on microglia and stimulates proliferation, survival and chemotaxis of these cells." (PMID 21319222, 2011). "However, our data support the view that the stimulation of Schwann cells by soluble NRG1 is responsible for the faster recovery observed in transgenic mice following nerve injury." (PMID 23437108, 2013). "NRG1 has recently been identified as a pro-nociceptive growth factor which is expressed by primary afferents, released within the dorsal horn following nerve injury and which promotes microgliosis and hence the development of neuropathic pain." (PMID 21319222, 2011). "Our data did not directly address whether IL-1β mediates NRG1 release, as has been shown with bleomycin-induced lung injury." (PMID 30813222, 2019).
mucinous lung adenocarcinoma (7 papers, 2015 to 2024). "More than 20% of patients with invasive mucinous adenocarcinoma of the lung were found to have a fusion of CD98hc and a driver oncogene protein Neuregulin 1 (NRG1)." (PMID 37823053, 2023). "We report for the first time that NRG1 fusions are driver alterations clearly associated with mucinous lung adenocarcinoma subtype of Caucasian patients and not exclusive of Asiatic population." (PMID 29515761, 2018). "Fourth, regarding overall survival, patients with NRG1 fusions, especially those with mucinous lung adenocarcinoma, have been shown to have reduced survival times compared to those without NRG1 fusions." (PMID 38957319, 2024). "NRG1 fusion was very rare in NSCLC, and mainly occurred in invasive mucinous lung adenocarcinoma." (PMID 34026636, 2021). "However, we found that the NRG1 fusion is not exclusive of mucinous lung adenocarcinomas but it can be also found with a very lower prevalence (3%) in non-IMA lung population." (PMID 29515761, 2018).
pancreatic adenocarcinoma (7 papers, 2023 to 2025). "In this study, most fusion-positive patients were identified by RNA-NGS, and the study resulted in the recent FDA approval of zenocutuzumab in December 2024 for patients with NSCLC and pancreatic adenocarcinoma harboring NRG1 fusions." (PMID 41091579, 2025). "The trial evaluated 65 patients with advanced or metastatic NRG1 fusion-positive NSCLC and 27 adults with advanced or metastatic NRG1 fusion-positive pancreatic adenocarcinoma who had disease progression following standard-of-care treatment." (PMID 40565299, 2025). "This agent is approved for the patients with advanced NSCLC and pancreatic adenocarcinoma harboring NRG1 gene fusions." (PMID 41154672, 2025). "The FDA granted accelerated approval to zenocutuzumab for advanced, unresectable or metastatic NSCLC and pancreatic adenocarcinoma harboring an NRG1 gene fusion with disease progression on or after prior systemic therapy on 4 December 2024." (PMID 40565299, 2025).
atherosclerosis (6 papers, 2008 to 2025). A disease characterized by the build-up of fatty material and calcium deposition in the arterial wall resulting in partial or complete occlusion of the arterial lumen. "Moreover, genetic factors, such as Neuregulin-1 genotype and catechol-o-methyltransferase gene polymorphism, were found to have moderating effects between work stress and atherosclerosis." (PMID 29614802, 2018). "The different NRG1 genotypes might, therefore, mark variation in both susceptibility to Type A and the development of atherosclerosis." (PMID 18798975, 2008). "Together, these data suggest NRG-1 as a critical factor for mediating the resistance to apoptosis conferred by Ang II in MASMCs, and NRG-1 may be a potential therapeutic target for vascular remodeling associated with RAAS overactivation in atherosclerosis, hypertension and vascular diseases." (PMID 31043588, 2019). "Novel research shows that NRG1 plays an important role in the occurrence and development of cardiovascular diseases, such as atherosclerosis, MI/IR, HF, cardiotoxicity, and arrhythmia." (PMID 36120374, 2022). "NRG-1 also inhibits cellular senescence, a key contributor to atherosclerosis, via ErbB452." (PMID 37336921, 2023). "The effect of job strain on early atherosclerosis is dependent on NRG1 genotype in men." (PMID 36120374, 2022). "Stimulation of ErbB3 by NRG1β has been reported to inhibit EC proliferation, and ErbB3 may be a potential therapeutic target of the NRG1-ErbB pathway against atherosclerosis." (PMID 36120374, 2022). "Second, NRG1 may play a role in cardiovascular disease such as coronary heart disease and atherosclerosis i.e. the suggested "outcomes" of Type A behavior." (PMID 18798975, 2008). "Furthermore, neuregulin-1 gene (NRG1) may play a role in cardiovascular disease such as atherosclerosis and coronary heart disease i.e. the suggested "outcomes" of Type A behavior." (PMID 18798975, 2008).
hepatocellular carcinoma (6 papers, 2018 to 2025). A malignant tumor that arises from hepatocytes. "MiR-296-5p is considered a valuable miRNA, and a report showed that the overexpression of miR-296-5p restricted the tumor development and aggression of hepatocellular carcinoma (HCC) by inactivating NRG1-Fra-2 signaling." (PMID 34860853, 2021). "In our study, we aimed to investigate the relationship between the NRG1 gene polymorphism and the cognitive function of patients with hepatocellular carcinoma (HCC) complicated with post‐traumatic stress disorders (PTSD) before and after the psychological intervention." (PMID 31944381, 2020).
infarction (6 papers, 2015 to 2023). A localised pathological necrosis of tissue resulting from obstruction of the blood supply usually by a thrombus, an embolus, or vascular torsion. "Whereas, RIPC protected against myocardial apoptosis and infarction, treatment with neutralizing-Nrg1 antibodies abolished the protective effect of RIPC." (PMID 34039018, 2021). "In a swine model of MI, intravenous NRG1 treatment initiated at 1 week post-infarction suppressed fibrosis and improved cardiac function." (PMID 27324127, 2016). "Considering the cardiomyocyte proliferation induced by MSC-ERBB4 injection together with the documented roles of NRG1-ERBB4 signaling in stimulating cardiomyocyte re-proliferation, we examined whether transplantation of MSC-ERBB4 could restore declined NRG1 in infarction region." (PMID 25996292, 2015).
Insulin resistance (6 papers, 2015 to 2025). Increased resistance towards insulin, that is, diminished effectiveness of insulin in reducing blood glucose levels. "Neuregulin-1 (NRG1) is known to suppresses the progression of inflammatory diseases, fibrosis, and insulin resistance." (PMID 40277942, 2025). "A previous study in cardiac cells showed that palmitate treatment induces insulin-resistance and also impairs NRG1 signaling." (PMID 26230680, 2015). "Chronic NRG1 treatment may also improve glucose tolerance in db/db mice, suggesting that the NRG1 pathway may represent a promising therapeutic target in conditions of insulin resistance." (PMID 26230680, 2015). "In contrast NRG1, FGF1 and IVM bind to site 2, but act as inhibitors of site 2-mediated pro-inflammatory action and insulin resistance (see Section 1)." (PMID 40943574, 2025). "Conversely, we show that NRG1 can strongly phosphorylate AKT at Ser473 and FOXO1 at Ser256 in db/db mice, suggesting that the NRG1 pathway in liver is functional also in conditions of insulin resistance." (PMID 26230680, 2015).
mental disorder (6 papers, 2015 to 2024). A disease that has its basis in the disruption of mental process. "Similar results were previously reported on neuregulin-1, the neurotrophic factor that could u-regulate AMPA receptor in GABAergic neurons and hence explained its benefit in the treatment of mental disorder." (PMID 29849706, 2018).
sarcoma (6 papers, 2021 to 2026). A usually aggressive malignant neoplasm of the soft tissue or bone. "NRG1 fusions have also been characterized in renal cell carcinoma, ovarian, breast, and some sarcomas." (PMID 38369520, 2024). "RNA-seq has since allowed the characterization of novel fusion genes such as CIC-NUTM1, TFCP2-rearranged, EWSR1-SSX1, as well as the identification of NTRK-rearranged sarcomas or NRG1-fused sarcomas." (PMID 35626152, 2022). "The scarcity of NRG1 fusions in sarcoma indicates that the development of NRG1 fusion-targeted therapy for sarcoma may not be high-priority." (PMID 40730881, 2025). "Other tumor types harboring an NRG1 fusion included PDAC, CRC, gastrointestinal stromal tumors (GISTs), squamous cell carcinomas (SCCs), breast, cholangiocarcinoma, thyroid, renal cell carcinoma, bladder, ovarian, neuroendocrine and sarcoma and are clinically actionable oncogenic drivers." (PMID 34680187, 2021).
cholangiocarcinoma (5 papers, 2022 to 2025). A carcinoma that arises from the intrahepatic biliary tree (intrahepatic cholangiocarcinoma) or from the junction, or adjacent to the junction, of the right and left hepatic ducts (hilar cholangiocarcinoma). "Responses have been observed in multiple tumor types including, but not limited to lung, pancreatic, cholangiocarcinoma, and ovarian cancer and with a variety of fusion partners for NRG1." (PMID 38369520, 2024). "Although rare (estimated in ~0.2% of all solid tumors) NRG1 fusions have been identified in several GI malignancies, including pancreatic ductal adenocarcinoma (~0.5%) (particularly in KRAS wild-type tumors), cholangiocarcinoma (~0.5%), and CRC (~0.1%)." (PMID 41153346, 2025).
chronic heart failure (5 papers, 2011 to 2025). "NRG-1/Cimaglermin is the full-length extracellular domain of NRG-1β3, also known as glial growth factor 2 (GGF2), which has been used in clinical development for chronic heart failure." (PMID 38638304, 2024). "Recent clinical studies demonstrated the efficacy and safety of NRG-1/Neucardin in human patients with congestive heart failure." (PMID 38638304, 2024). "Nrg1 has reported effects on cell survival, metabolism, angiogenesis, and myofiber structure in addition to cardiomyocyte proliferation, influences that are possibly reflected by functional improvement after Nrg1 infusion in congestive heart failure patients." (PMID 25830562, 2015). "The heart function of DCM rats with chronic heart failure was significantly improved by NRG-1, supporting the rationale of replenishing NRG-1 as an optional selection for DCM therapy, although further clinical studies are required." (PMID 21798071, 2011). "Recombinant human Nrg1 (Neucardin) has completed phase III trials as a treatment for chronic heart failure, although those results are not yet available." (PMID 41256601, 2025).
cognitive decline (5 papers, 2020 to 2025). "Surprisingly, AD patients with low CSF NRG1 levels had a tendency to have a more rapid cognitive decline as compared to patients with higher CSF NRG1 levels." (PMID 32690068, 2020). "A longitudinal follow-up study of AD patients revealed a trend (p = 0.08) between CSF NRG1 levels and cognitive decline." (PMID 32690068, 2020). "In AD patients, CSF NRG1 levels negatively correlate with cognition and show a correlation trend with cognitive decline." (PMID 32690068, 2020). "A correlation was found between CSF NRG1 levels and cognitive status, and a trend with cognitive decline was observed in AD patients." (PMID 32690068, 2020). "Similarly, NRG1 (neuregulin-1) was upregulated in our dataset and others, supporting its role in synaptic dysfunction, cognitive decline, and microglial dysregulation in 10.13039/100020014AD." (PMID 40602528, 2025). "CSF NRG1 levels are already enhanced in MCI-AD patients and modulating the increased activity of synaptic NRG1 in AD might represent an original therapeutic strategy to alter abnormal signaling linked to cognitive decline and neurodegeneration." (PMID 32690068, 2020). "In CSF, two studies including our prior work have reported modified NRG1 levels in AD patients compared with controls and to patients with non-AD-related cognitive decline." (PMID 35606871, 2022). "Increased levels of CSF NRG1 in AD compared with controls and with non-AD-related cognitive decline have been reported in the literature, including our prior work." (PMID 35606871, 2022). "The reason why CSF NRG1 levels tend to be negatively correlated with cognitive decline in AD patients is not known." (PMID 32690068, 2020). "Targeting brain NRG1 activity and synaptic NRG1 pathway in MCI-AD and AD patients could be a possible new way to attenuate cognitive decline and neuronal demise." (PMID 32690068, 2020). "The purpose of our study was to investigate plasma NRG1 levels in a cohort of patients with cognitive decline due to AD, non-AD-related cognitive decline, and neurological controls and to assess its association with core AD CSF biomarkers, CSF synaptic markers, and cognitive status." (PMID 35606871, 2022).